TRPS1 (transcriptional repressor GATA binding 1)
Diseases named in the same sentence as TRPS1 in open-access papers (continued):
Sharing a sentence is not in itself a finding about the gene and the disease.
breast carcinoma (continued). "Finally, we demonstrate that TRPS1 expression is elevated in luminal breast cancer cells and luminal breast cancer tissues as compared with other breast cancer subtypes." (PMID 25277197, 2014). "In ERα-negative breast cancer, we found TRPS1 to be positively associated with vimentin, SMA and slug." (PMID 24934762, 2014). "There are many possible explanations for the different association between the molecular markers with TRPS1 in ERα-positive and ERα-negative breast cancer." (PMID 24934762, 2014). "Using BT474 human breast cancer cells, we first confirmed that TRPS1 could be successfully knocked down by siRNA at both the mRNA and protein levels." (PMID 25277197, 2014). "This was further validated by the elevated TRPS1 expression in two luminal breast cancer cell lines (MCF7 and BT474 cells) as compared with the basal breast cancer cell line, MDA-MB-231, and non-cancerous MCF10A cells, which are classified as basal subtype according to Neve's published work." (PMID 25277197, 2014). "Recently, TRPS1 mRNA was also detected in human breast cancer xenografts." (PMID 24709795, 2013). "Collectively, TRPS1 is considered to be related to a better clinical prognosis of breast cancer." (PMID 24709795, 2013). "Moreover, Trps1 has been found to be closely related to tumorigenesis, invasion, and metastasis in prostate and breast cancers." (PMID 24709795, 2013). "For example, PHF20L1, BCAS3, TAOK1, PCGF2, and TRPS1 are fused in other breast cancers." (PMID 23260012, 2012). "Interestingly, in most breast cancer cell lines, the expression of TRPS1 was high compared to the expression levels of EIF3S3 and MYC." (PMID 14997205, 2004). "Furthermore, bioinformatic analysis and RNA binding protein immunoprecipitation assay reveal that AF178030.2 can directly bind with trichorhinophalangeal syndrome-1 (TRPS1), an oncogene in breast cancer, and downregulate its expression in paclitaxel-resistant TNBC cells." (PMID 35399640, 2022). "However, how TRPS1 contributes to breast cancer is still obscure." (PMID 30563971, 2018). "Also, breast cancer patients with high TRPS1 and low TP63 expression had better overall survival." (PMID 30563971, 2018). "In addition, TRPS1 stimulates cell proliferation and angiogenesis in breast cancer." (PMID 26183398, 2015). "Indeed, TRPS1 gene overexpression in more than 90% of breast cancers has been reported." (PMID 24886451, 2014). "The TRPS1 gene is localized on human chromosome 8q23-24.1, a region highly amplified in several cancers, especially prostate cancer and breast cancer, indicating that TRPS1 may be overexpressed during development or progression of these endocrine-related cancers." (PMID 23762846, 2013). "Studies show that its sensitivity is lower than TRPS1, but it can be used alongside SOX10 to help identify the basal-like subtype of breast cancer." (PMID 40822238, 2025). "The trichorhinophalangeal syndrome protein 1 (TRPS1) is a zinc finger transcription factor belonging to the GATA family, playing a pivotal role in breast carcinoma development." (PMID 38902365, 2025). "TRPS1 and GATA3 immunohistochemical stains should be considered for differentiating primary from secondary breast cancer, while CDX2 is in favor of primary gastric cancer." (PMID 40936680, 2025). "With GATA3 and TRPS1, more specific breast cancer markers are available that showed 55.4% (GATA3,) and 77.8% positivity (TRPS1, manuscript in revision) in triple-negative breast cancers in our tumor cohort." (PMID 38790919, 2024). "In contrast, TRPS1 has been shown to have a higher sensitivity across all molecular subtypes of breast carcinoma, particularly in TNBC, where TRPS1 is more consistently expressed compared with mammaglobin." (PMID 39518009, 2024). "While both markers demonstrate a high specificity for breast tissue, TRPS1 surpasses GCDFP-15 in terms of sensitivity, particularly in poorly differentiated and basal-like breast carcinomas." (PMID 39518009, 2024).
breast carcinoma (continued). "As in breast cancer cells, the expression of YAP target genes was strongly induced by depletion of TRPS1." (PMID 38702730, 2024). "For instance, studies comparing TRPS1 antibody clones found that MSVA-512R and 8D11 consistently provide a strong nuclear positivity in the vast majority of breast carcinoma cases." (PMID 39518009, 2024). "Second, we analyzed data from the Cancer Dependency Map project and found that sensitivity to TRPS1 knockout was correlated with sensitivity to ESR1 knockout and significantly enriched among luminal breast cancer cell lines." (PMID 38377146, 2024). "Conversely, IHC markers for breast cancer (BC) include GATA3, GCDFP-15, TRPS1, estrogen receptor (ER), progesterone receptor (PR), and human epidermal growth factor receptor 2 (HER2)." (PMID 38905573, 2024). "TRPS1 (trichorhinophalangeal syndrome type 1) is a transcription factor of the GATA family, and has been found to be a relatively specific marker of breast cancers through TCGA (The Cancer Genome Atlas) data mining." (PMID 37012444, 2023). "Nonetheless, TRPS1 and INSM1 were reliable markers of predicted breast carcinoma (75.0%) and neuroendocrine tumors (83.3%), respectively." (PMID 38041048, 2023). "As for the TRPS1 (transcriptional repressor GATA binding 1) gene, its overexpression has been recently shown to drive genome evolution in breast carcinomas." (PMID 37297004, 2023). "We firstly treated endometrial cancer cells and mammary cancer cells with different doses of MPA, and tested its effects on TRPS1 at multiple time points." (PMID 37344459, 2023). "MGP, TRPS1, and GATA3 were positive in 1075/1201 (89.5%), 1109/1201 (92.3%), and 922/1201 (76.8%) breast carcinomas, respectively." (PMID 36284362, 2022). "Using mRNA sequencing and proteomic data from TCGA and CPTAC of 24 different solid tumors, we identified six potential genes that are specifically upregulated in breast carcinoma: NAT1, MGP, SCGB2A2, LMX1B, TFAP2B, and TRPS1." (PMID 36284362, 2022). "We next compared MGP, TRPS1, and GATA3 expression in 1201 breast carcinoma cases of different subtypes, including 140 metaplastic breast carcinoma cases, using immunochemistry staining." (PMID 36284362, 2022). "We compared MGP, TRPS1, and GATA3 expression in different subtypes of breast carcinoma of (n = 1201) using IHC." (PMID 36284362, 2022). "We further observed that only TRPS1 and matrix Gla protein (MGP) had comparable expression in luminal A/B, HER2-enriched, basal-like and normal-like subtypes of breast cancer." (PMID 36284362, 2022). "Frequently affected genes by CNVs in Chinese breast cancer patients were ERBB2 (25%), MIEN1 (25%), GRB7 (24%), TRPS1 (6%), MYC (6%), ERLIN2 (6%), PLPP5 (6%), NSD3 (6%), FGFR1 (6%), and CCND1 (5%)." (PMID 33173047, 2020). "Both overexpression and knockdown of TRPS1 assays were performed to examine the effect of TRPS1 on histone deacetylase 2 (HDAC2) protein level and luminal breast cancer cell proliferation." (PMID 30071870, 2018). "To investigate the functional relationship between TRPS1 and YAP target gene expression, we used two breast cancer cell lines, MCF7 and T47D, expressing high levels of TRPS1 on protein level." (PMID 30082728, 2018). "TRPS1 is able to repress target genes containing a GATA-binding site in their promoter and is commonly overexpressed in breast cancer compared to normal tissue." (PMID 30082728, 2018). "Taken together, our results suggested that elevated expression of TRPS1 nucleates CHD4/NuRD(MTA2) complex to repress ΔNp63 expression to reduce cell migration and invasion of breast cancer cells and better survival." (PMID 30563971, 2018). "Trichorhinophalangeal syndrome type 1 (TRPS1) gene, a GATA-type transcription factor, has been found to be highly expressed in breast cancer." (PMID 24934762, 2014).
breast carcinoma (continued). "Recently gene expression profiling and immunohistochemistry (IHC) studies have been identified Tricho-rhino-phalangeal syndrome-1 gene (TRPS1), a new GATA family member, to be highly prevalent gene in breast cancer." (PMID 24934762, 2014). "The breast cancer basal-like subtype-specific miRNAs, miR-221 and miR-222, promote EMT in breast cancer by targeting TRPS1 (trichorhinophalangeal syndrome type 1) which inhibits EMT by repressing ZEB2 expression." (PMID 22382486, 2012). "Whereas in breast cancer cells, TRPS1 mainly bound to enhancer regions via its GATA domain, our CUT&RUN demonstrate a promoter-proximal binding pattern that is potentially mediated by TRPS1’s C2H2 zinc fingers." (PMID 38702730, 2024). "In detail, all but one (18/19, 94.7%) of the metastatic breast carcinomas showed diffuse and strong TRPS1 positivity (histoscore 12), regardless of histological subtype." (PMID 39449380, 2024). "For instance, breast cancer metastases in the lung can histopathologically resemble primary lung adenocarcinomas, but TRPS1 staining is consistently positive in breast cancer and negative in primary lung cancers." (PMID 39518009, 2024). "Studies that assessed TRPS1 expression across various breast cancer subtypes revealed that approximately 5–10% of TNBC cases are TRPS1-negative." (PMID 39518009, 2024). "A further exploration of genes enriched in cancer cells relative to normal cells using Kaplan–Meier Plotter revealed that breast cancer patients with elevated expression of GRHL1, TRPS1, and ZHF217 have a decreased rate of survival relative to patients with low expression of these genes." (PMID 37627195, 2023). "TRPS1 expression is not specific to breast cancer, and a high percentage of SGTs (86% overall; 75% intermediate to high) also show positivity." (PMID 36810569, 2023). "When combining GATA3, TRPS1, and MGP, we observed that 797/1201 (66.4%) of the enrolled breast carcinoma cases were positive for all three markers, including 452/565 (80.0%), 238/352 (67.6%), and 107/284 (37.7%) in the ER/PR+, HER2+, and TNBC subgroups, respectively." (PMID 36284362, 2022). "Trps1 (GATA protein) has been shown as a potential tumor marker (cytologic) in a variety of cancers (osteosarcoma, malignant tumor, prostatic carcinoma, and breast cancer) and plays an imperative role in the differentiation and enlargement of mammals." (PMID 35885958, 2022). "In the current study, MGP was rarely expressed in lung adenocarcinomas (0.7%), which is lower than the previously reported positivity of GATA3 (∽8%,) and TRPS1 (2–3%,), indicating that MGP is a good marker to differentiate breast cancer from lung adenocarcinoma." (PMID 36284362, 2022). "FOXA1 binding sites are known to define lineage-specific enhancers in luminal breast cancer cells and several luminal-specific transcription factor motifs (GATA3, TRPS1, etc.) were also significantly enriched in the set of differentially accessibly ATAC-seq sites." (PMID 35353838, 2022). "Correlation between TRPS1 expression and BCRP expression in breast cancer." (PMID 32695669, 2020). "TRPS1 demonstrated a very strong nuclear staining in 27 out of 27 breast cancer patients, indicating that TRPS1 expression does not commonly get lost in breast cancer." (PMID 30082728, 2018). "We further analyzed the expression data of 1762 breast cancers retrieved from GEO and found a statistically significant negative correlation of the expression between TRPS1 and TP63 (r = −0.3387, p < 0.001) and between CHD4 and TP63 (r = −0.3751, p < 0.001)." (PMID 30563971, 2018). "TRPS1 expression was not regulated by ER signalling since estrogen withdrawal using charcoal-stripped serum did not affect TRPS1 gene or protein expression in ERα-positive breast cancer cell lines." (PMID 24934762, 2014). "TRPS1 gene in human has been found to be overexpressed in breast cancer, expressed in more than 90% estrogen receptor α (ERα) positive and negative breast cancer subtype." (PMID 24934762, 2014).
breast carcinoma (continued). "Realizing the potential of TRPS1 gene as the new EMT marker, we focused our work in elucidating different roles and clinical relevance of TRPS1 in ERα-positive and ERα-negative breast cancer subtypes." (PMID 24934762, 2014). "Contrary to earlier assumptions, TRPS1 is not specific to mammary tumors." (PMID 40969274, 2025). "TRPS1-negative cases emphasize the importance of a multi-marker approach in breast cancer diagnostics, as relying solely on TRPS1, especially in challenging cases, could lead to diagnostic errors." (PMID 39518009, 2024). "As such, we do not know which genes TRPS1 directly regulates and whether these genes are important for breast cancer cell growth and proliferation." (PMID 38377146, 2024). "The 25 TRPS1-negative cases displayed various staining with other breast cancer markers." (PMID 37012444, 2023). "However, we do not know how TRPS1 regulates target genes to mediate these breast cancer patient and cellular outcomes." (PMID 37461612, 2023). "Since MGP and TRPS1 showed high expression in luminal A/B, HER2-enriched, TNBC/basal-like, and normal-like subtypes according to the PAM50 subtyping, we selected MGP, TRPS1, and GATA3 for further validation in 1201 cases of breast carcinoma of different subtypes and normal breast tissues." (PMID 36284362, 2022). "This is supported by our analyses of the publically available TCGA data sets for breast cancer which show that the TRPS1 locus is not deleted in human breast cancer patients but is rather amplified in a high fraction of patients leading to increased TRPS1 mRNA expression." (PMID 30082728, 2018). "Since GATA3 and TRPS1 were found to specifically high express in breast cancer among all GATA members, we next performed further exploration on the potential roles of GATA3 and TRPS1 in BC, in connection with other featured biomarkers according to molecular subtypes of breast cancer." (PMID 28423734, 2017). "The absence of TRPS1 expression in ER− BCC lines could be related to its significant down-regulation in ER− breast cancer samples; however, this finding needs to be validated in a wider number of ER− BCC lines and by quantitative immunohistochemistry analysis." (PMID 26183398, 2015). "As TRPS1 may be a critical regulator of EMT during breast cancer initiation and progression, the expression of EMT markers, including E-cadherin, β-catenin, vimentin, SMA and slug, were stained in human breast cancer TMA." (PMID 24934762, 2014). "However, TRPS1 is often co-amplified along with the rest of the chromosomal segment 8q23–q24, where the proto-oncogene MYC resides, making it difficult to discern whether TRPS1 amplification is a driver of breast cancer progression." (PMID 38377146, 2024). "However, previous studies showed that higher TRPS1 expression, when analysed using univariate and multivariate models, predicted better overall survival (OS) and disease-free survival (DFS) in a subgroup of ERα+, stage I/II breast cancer patients who received endocrine therapy only." (PMID 24934762, 2014). "Initial studies showed that TRPS1 was not expressed in bladder cancers and therefore, TRPS1 can be considered superior to GATA3 when the differentials include bladder and breast cancers." (PMID 40025593, 2025). "Metastatic breast carcinoma cells typically exhibit positive expression of mammary epithelial differentiation markers (e.g., GATA, Mammaglobin, ER/PR, TRPS1) and negative expression of thyroid follicular cell markers (e.g., Thyroglobulin, TTF-1, PAX-8)." (PMID 41199830, 2025). "Immunohistochemistry (TRPS1, GATA-3) and histomorphology (absence of apocrine differentiation) are pivotal for distinguishing accessory breast carcinoma from mimics." (PMID 40978063, 2025). "For the non-cancer adipose-breast network that we applied to the breast cancer GWAS, Downstreamer prioritised seven known breast cancer driver genes among the top 100 genes: CREBBP, TRPS1, ARID1A, ARID1B, XBP1, SPEN and NUMA1." (PMID 39010058, 2024).
breast carcinoma (continued). "The anti-correlation between TRPS1 and YAP activity was not confined to a specific breast cancer subtype." (PMID 30082728, 2018). "Furthermore, basal-like breast carcinomas, which overlap with TNBC, also show variable TRPS1 expression, with a small percentage of cases showing no TRPS1 staining." (PMID 39518009, 2024).